ATG7 (autophagy related 7)
Description:
E1-like activating enzyme involved in the 2 ubiquitin-like systems required for cytoplasm to vacuole transport (Cvt) and autophagy. Activates ATG12 for its conjugation with ATG5 as well as the ATG8 family proteins for their conjugation with phosphatidylethanolamine. Both systems are needed for the ATG8 association to Cvt vesicles and autophagosomes membranes. Required for autophagic death induced by caspase-8 inhibition. Facilitates LC3-I lipidation with phosphatidylethanolamine to form LC3-II which is found on autophagosomal membranes. Required for mitophagy which contributes to regulate mitochondrial quantity and quality by eliminating the mitochondria to a basal level to fulfill cellular energy requirements and preventing excess ROS production. Also plays a key role in the maintenance of axonal homeostasis, the prevention of axonal degeneration, the maintenance of hematopoietic stem cells, the formation of Paneth cell granules, as well as in adipose differentiation. Plays a role in regulating the liver clock and glucose metabolism by mediating the autophagic degradation of CRY1 (clock repressor) in a time-dependent manner (By similarity).
Synonyms: APG7-like; APG7L; GSA7; DKFZp434N0735; SCAR31
Tractability: Small molecule: a high-quality ligand is known. Antibody: its Gene Ontology location is reachable by antibodies, with high confidence; the Human Protein Atlas places it where antibodies can reach. PROTAC: UniProt records ubiquitination sites on it; ubiquitination databases record sites on it; its protein half-life has been measured; a small molecule that binds it is known.
Target class: Enzyme
Gene: Protein-coding gene on chromosome 3 (11,272,309 to 11,557,665, forward strand). Ensembl gene ENSG00000197548.
Subcellular location: Cytoplasm; Preautophagosomal structure
Subcellular location (Human Protein Atlas): Cytosol; Connecting piece; Flagellar centriole; Mid piece; Nucleoplasm; Plasma membrane
Pathways (Reactome):
Disease: Dengue Virus Attachment and Entry; Signaling by BRAF and RAF1 fusions
Immune System: Antigen processing: Ubiquitination & Proteasome degradation; Neutrophil degranulation
Autophagy: Macroautophagy
Gene Ontology:
Molecular function: Atg12 activating enzyme activity; protein binding; protein homodimerization activity; Atg8 activating enzyme activity; ubiquitin-like modifier activating enzyme activity
Biological process: autophagosome assembly; autophagy; cellular response to hyperoxia; cellular response to starvation; cellular response to stress; defense response to virus; macroautophagy; mitophagy; positive regulation of apoptotic process; positive regulation of protein catabolic process; positive regulation of protein modification process; protein lipidation; protein lipidation involved in autophagosome assembly; cellular response to nitrogen starvation; piecemeal microautophagy of the nucleus; regulation of circadian rhythm; positive regulation of catabolic process; regulation of apoptotic process; regulation of cell development; regulation of hemopoiesis; response to nutrient levels; synaptic vesicle cycle
Cellular component: autophagosome; cytoplasm; phagophore assembly site; axoneme; cytosol; extracellular region; ficolin-1-rich granule lumen; secretory granule lumen; dopaminergic synapse; perinuclear region of cytoplasm; presynapse
Genetic constraint (gnomAD): Loss-of-function variants: 63 observed, 78.92 expected, observed/expected ratio (o/e) 0.8, 90% interval 0.65 to 0.99. The upper end of that interval is the gene's LOEUF score, 0.99, which puts it in group 4 of 6, group 1 being the genes least tolerant of losing a copy. Missense variants: 782 observed, 886.46 expected, observed/expected ratio (o/e) 0.88, 90% interval 0.83 to 0.94. Synonymous variants: 285 observed, 322.19 expected, observed/expected ratio (o/e) 0.88, 90% interval 0.8 to 0.98.
Gene-disease validity (ClinGen):
ClinGen rates the evidence that ATG7 causes each of these diseases.
spinocerebellar ataxia, autosomal recessive 31 (autosomal recessive): Strong.
Homologues: Orthologues: macaque ATG7 (99% identical), chimpanzee ATG7 (98% identical), rabbit ATG7 (94% identical), dog ATG7 (94% identical), pig ATG7 (93% identical), mouse Atg7 (93% identical), guinea pig ATG7 (92% identical), rat Atg7 (87% identical), tropical clawed frog atg7 (74% identical), zebrafish atg7 (69% identical), Caenorhabditis elegans atg-7 (40% identical), Drosophila melanogaster Atg7 (40% identical). Paralogues in human: UBA1 (16% identical), UBA6 (15% identical), UBA7 (14% identical), MOCS3 (13% identical), UBA5 (9% identical), UBA3 (8% identical), NAE1 (8% identical), UBA2 (7% identical), SAE1 (6% identical).
Diseases named in the same sentence as ATG7 in open-access papers:
ATG7 is named in the same sentence as 313 diseases in open-access papers, as found by Europe PMC text mining. Sharing a sentence is not in itself a finding about the gene and the disease. The quoted sentences say what the papers report.
breast cancer (77 papers, 2013 to 2026). A primary or metastatic malignant neoplasm involving the breast. "To follow up on our findings that Atg7-deficient fibroblasts regulate breast cancer progression through paracrine signals in vivo and in vitro, we next investigated the expression and function of ATG7 in fibroblasts of different breast cancer patient samples." (PMID 40707430, 2025). "In another study, elevated ATG7 expression was associated with bladder cancer and lung cancer, and high levels of ATG7 expression were associated with poor prognosis in breast cancer patients." (PMID 40276062, 2025). "This was recently identified following Atg7 loss of function in a breast cancer cell line, which resulted in a compensatory increase in outer‐membrane derived MDV flux." (PMID 40641845, 2025). "Detailed regulatory mechanisms showed that ATG7-deficient fibroblasts secrete a new miRNA (miR-6803b) and are then transported into breast cancer cells by exosomes." (PMID 40707430, 2025). "Consistently, the drug‐activated autophagy was proven to reduce the secretion of IL‐6 in chondrocytes, while the suppression of autophagy by deleting Atg7 caused increased export of IL‐1β, IL‐6 and IL‐8 in adipocytes and breast cancer cells." (PMID 33963627, 2021). "Autophagy-deficient HRASV12-transformed breast cancer cell lines display reduced invasive protrusions in genetic knockdown models (including ATG7, ATG12, and ATG3) and after pharmacological inhibition (chloroquine or bafilomycin A1)." (PMID 27933272, 2016). "Loss of ATG7 expression results in fibroblasts acquiring the hallmarks of cancer-associated fibroblasts (CAFs), which finally promote the proliferation, metastasis of breast cancer in vivo and vitro." (PMID 40707430, 2025). "However, the effects of ATG7 gene mutation caused by genetic instability in peritumoral fibroblasts in breast carcinoma on tumorigenesis and progression as well as its functional role remain poorly understood." (PMID 40707430, 2025). "Moreover, Atg7 variant rs8154 is a new prognostic marker for breast cancer based on in silico analysis." (PMID 38553562, 2024). "In a recently published study, we described a genetic interaction and functional cooperation between Atg7, an essential autophagy gene, and Palb2, a breast cancer susceptibility gene, in the maintenance of mitochondrial function, redox homeostasis, and neuronal viability." (PMID 40396054, 2022). "Specifically, a loss of ATG7 expression stimulates the conversion of fibroblasts into activated fibroblasts and results in the acquisition of characteristic CAFs functions that promote breast cancer epithelial cell proliferation, metastasis and stemness through exosome-mediated miR-6803b." (PMID 40707430, 2025). "To confirm the role of exosomal miR-6803b, we exposed breast cancer cells to exosomes derived from ATG7−/− HFF-1, either in isolation or in combination with a miRNA inhibitor." (PMID 40707430, 2025). "In this study, we demonstrate that abnormal ATG7 expression in fibroblasts promotes breast cancer progression through paracrine signaling." (PMID 40707430, 2025). "Taken together, these results reveal that Atg7−/− fibroblasts promote breast cancer cell proliferation, induce EMT and increase tumor metastasis through paracrine signals of exosomes." (PMID 40707430, 2025). "Herein, we revealed that aberrantly low expression of ATG7 in breast stroma is clinically relevant to breast cancer progression." (PMID 40707430, 2025). "On the other hand, the deletion of autophagy-related genes has been shown to promote tumor formation, such as the deletion of ATG7 in liver tumors and the deletion of Beclin-1 in breast cancer." (PMID 40917720, 2025). "In summary, our comprehensive investigation reveals a pivotal role for ATG7 in breast cancer progression, with its distinct impact on stroma significantly influencing patient outcomes." (PMID 40707430, 2025).
breast cancer (continued). "Utilizing microarray data retrieved from the GEO database (GSE27018), we found that compared with that in monoculture cells, ATG7 expression in breast cancer epithelial cells was retained when cocultured with breast tumor tissue fibroblasts." (PMID 40707430, 2025). "After demonstrating the specificity of ATG7 antibody in immunohistochemistry, we examined ATG7 expression in different breast cancer patient samples by immunohistochemistry analysis using staining intensity score." (PMID 40707430, 2025). "Consistently, GEO database (GSE100534) analysis revealed that diminished expression of ATG7 was evident in metastatic breast cancer tissues compared to primary breast tissues." (PMID 40707430, 2025). "Remarkably, the anomalous downregulation of ATG7 in relapsed breast cancer patients was predominantly observed in the stromal region as opposed to the epithelium." (PMID 40707430, 2025). "Correspondingly, Scratch/Transwell assays also indicated that Atg7−/− MEFs exhibited stronger induction of breast cancer epithelial cell migration." (PMID 40707430, 2025). "The results showed that Rab27a knockdown significantly reduced the ability of Atg7−/− MEFs to stimulate breast cancer cell malignant progression." (PMID 40707430, 2025). "In the present study, our findings suggest that ATG7 is a pivotal regulator of the expression of miR-6803b, which is an important factor regulating breast cancer progression." (PMID 40707430, 2025). "Multiple in vitro investigations have demonstrated an upregulation of Beclin-1, ATG7, LC3-II, and p62 expression levels in malignancies associated with breast cancer (BC) and chronic myeloid leukemia (CML)." (PMID 38794148, 2024). "Mitochondrial DNA accumulation was shown to activate the STING pathway when combining autophagy inhibition (by hydroxychloroquine treatment or knockout of Atg5 or Atg7) with irradiation in breast cancer models." (PMID 38506049, 2024). "Circ_0092276 can repress ATG7 via sponging miR-384, thus effecting autophagy and proliferation as well as repressing apoptosis of breast cancer cells." (PMID 38338839, 2024). "Suppression of autophagy through ATG7/12 silencing in breast cancer cells increases FA and decreases the breast cancer cell migration rate." (PMID 36831154, 2023). "In agreement, inhibition of autophagy-related 7 (ATG7) promotes dormant breast cancer cell death and reduces the total lung metastatic burden." (PMID 35158815, 2022). "In line with breast cancer stem cells, knockdown of ATG7 in immortalized pancreatic stellate cells reduces not only IL-6 secretion but also the release of ECM proteins such as type I collagen and fibronectin." (PMID 35927755, 2022). "Hsa_circ_0092276 supported autophagy and DOX resistance in breast cancer by regulating the miR 348/ATG7 (Autophagy related 7) axis." (PMID 37304411, 2022). "For instance, ATG7-dependent autophagy facilitated promoting erlortinib resistance and silencing ATG7 overcame resistance of breast cancer cells to erlortinib." (PMID 35690866, 2022). "Inhibition of autophagy by knocking down ATG7 or beclin 1 in breast cancer stem cells diminishes IL-6 secretion, cell survival as well as mammosphere formation." (PMID 35927755, 2022). "In fact, the double CKO mice practically all succumb to neurodegeneration prior to any mammary tumor development, preventing any assessment of Atg7 in mammary tumorigenesis induced by inactivation of Palb2." (PMID 40396054, 2022). "Hsa_circ_0085131 and hsa_circ_0092276 serve as competitive endogenous RNAs (ceRNAs) to elevate autophagy-associated factor ATG7 expression, thus enhancing CDDP resistance in NSCLC and doxorubicin (DOX) resistance in breast cancer." (PMID 35070998, 2021). "Previously, we had demonstrated that over-expression of circRNA circCDYL promoted progression of HER2-negative (HER2–) breast cancer via miR-1275-ULK1/ATG7-autophagic axis." (PMID 34395434, 2021).
breast cancer (continued). "ATG7 inactivation enhances the effectiveness of anti‐cancer therapeutics in lung and breast cancer cell treatment." (PMID 34725936, 2021). "In a recent study, pharmacologic or genetic inhibition of autophagy-related 7 gene (ATG7) in dormant breast cancer cells, resulted in significantly decreased cell survival." (PMID 34064392, 2021). "Treatment caused a dose-dependent increase in the total protein levels of LC3A/B, Beclin-1 (Atg6), Atg5, Atg7, and Atg16L1 in BT-474 breast cancer cells." (PMID 25580621, 2015). "Heat shock factor 1-controlled transcriptional expression of ATG7 is inversely correlated with the chemotherapeutic prognosis of breast cancer patients." (PMID 26404030, 2015). "As has been reported in hepatic cells, Atg7 is required for Keap1 degradation in two different model systems: MDA-MB-231 breast cancer cell lines and mouse embryonic fibroblasts." (PMID 24681637, 2014). "Knockdown of Atg7 siRNA also sensitized breast cancer cells to 3-BrPA, indicating that autophagy was responsible for 3-BrPA resistance." (PMID 25053988, 2014). "In particular, a higher concentration of MitoQ (5 μM) was required to induce autophagy in MEF Atg7+/+ than in breast cancer cells, which is consistent with previous observations." (PMID 24681637, 2014). "Since intracellular ROS levels are closely linked to the regulation of autophagy, we followed the autophagy biomarkers beclin-1, LC-3, Atg7 and Atg5 protein levels in breast cancer cells in which the CYP2E1 was either ectopically expressed or silenced." (PMID 24207099, 2013). "Our hypothesis posits that the poor prognosis observed in breast cancer patients is primarily due to the diminished expression of ATG7 within the fibroblasts." (PMID 40707430, 2025). "To determine the role of ATG7 in breast cancer progression, we assembled a cohort of 140 primary breast cancer tumors, spanning diverse TNM stages, a standardized classification system used to assess cancer progression based on tumor size (T), lymph node involvement (N), and distant metastasis (M)." (PMID 40707430, 2025). "In this report, starting from clinical evidence and focusing on the role of ATG7 expression in the fibroblasts in the progression of breast cancer, we reveal a communication mode between breast cancer cells and fibroblasts that contributes to the generation of the tumor and its progression." (PMID 40707430, 2025). "Thus, our results indicate that ATG7 expression in fibroblasts plays a vital role in regulating breast cancer tumorigenesis and progression by modifying stromal–epithelial crosstalk and remodeling the tumor microenvironment (TME)." (PMID 40707430, 2025). "Subsequent Western blot analysis showed that fibroblasts derived from patient samples #4 and #5 (TNM stage II) had significantly lower levels of ATG7 protein than fibroblasts from other samples (including 1# hyperplasia and 2# and 3# breast cancer of TNM stage I)." (PMID 40707430, 2025). "Thus, our results suggest that miR-6803b in exosomes secreted by ATG7−/− fibroblasts, as a messenger from fibroblasts to cancer cells, plays a crucial role in inducing breast cancer progression and promoting tumorigenesis." (PMID 40707430, 2025). "To further investigate the role of exosomes in the crosstalk between fibroblasts and breast cancer cells, we generated Atg7−/− MEFs in which Rab27a was constitutively knocked down by short hairpin RNAs (shRNAs), resulting in cells with abnormal exosomal function." (PMID 40707430, 2025). "Interestingly, through clinical data mining and preliminary in vitro experiments, we found that breast cancer cells significantly induced low expression of ATG7 in fibroblasts compared with normal breast epithelial cells (data not shown)." (PMID 40707430, 2025). "Interestingly, when ATG7 was restored in Atg7−/− MEFs, its promoting effect on breast cancer cells was significantly reduced." (PMID 40707430, 2025).